ACE (angiotensin I converting enzyme)
Diseases named in the same sentence as ACE in open-access papers (continued):
Sharing a sentence is not in itself a finding about the gene and the disease.
angina (46 papers, 2006 to 2025). "Yoshida revealed that the endpoints of the study (cardiac death, reccurent MI or unstable angina) were significantly associated with the ACE ID polymorphism (RR = 4.49), and that the DD/ID genotype was associated with a higher occurrence of the endpoints." (PMID 21162760, 2010). "Both ACE inhibitors (0.81; 95% CrI 0.65–0.96; moderate confidence) and ARBs (0.76; 95% CrI 0.61–0.98; moderate confidence) were associated with a reduced risk of angina compared with placebo." (PMID 26954482, 2016). "Interestingly, ACE inhibitor use was also associated with an increased risk of angina hospitalization." (PMID 24800739, 2014). "We suspect that baseline ACE inhibitor use in our current cohort is likely a marker of more advanced vascular disease, which may have contributed to an increased risk of angina hospitalization." (PMID 24800739, 2014). "Additionally, when ACE inhibitor use was included in a model that contained cTFC at cut-point 35, it was associated with a higher risk of hospitalization for angina (HR 2.04 [95% CI 1.15, 3.59], P = 0.014)." (PMID 24800739, 2014). "Drug therapy for stable angina includes antiplatelet agents, lipid-lowering drugs, beta-blockers, and angiotensin I-converting enzyme (ACE) inhibitors, which help decrease the incidence of myocardium ischemia and increase patient survival." (PMID 27822397, 2016). "We have previously shown that patients randomized to an ACE inhibitor had greater improvement in angina severity as compared to those who received placebo." (PMID 24800739, 2014). "Analysis of cardiac ventricle samples taken during biopsies from patients with stable and unstable angina revealed that the patients with unstable angina synthesize more Ang II and have higher expressions of angiotensinogen, angiotensin converting enzyme (ACE) and AT1R genes." (PMID 36430892, 2022). "Furthermore, to study whether treatment with ACE inhibitor is indicated in patients with angina and normal blood pressure." (PMID 29883497, 2018). "However, when ACE inhibitor use, white race, and cTFC at cut-point 35 were all included in a predictive model of hospitalization for angina, only cTFC provided independent prediction of hospitalization for angina." (PMID 24800739, 2014). "Other significant factors included a history of alcohol consumption, abnormal serum sodium levels, low usage rates of ACE inhibitors, intraoperative hypotension (mean arterial pressure [MAP] ≤ 60 mmHg for 5–10 min), and a history of angina pectoris." (PMID 40809288, 2025). "The patient's course was managed with dual antiplatelet therapy, beta-blockers, angiotensin-converting enzyme (ACE) inhibitors, and statins, with anti-anginal agents added upon the recurrence of angina." (PMID 40636625, 2025). "The use of aspirin, beta-blockers, ACE inhibitors and statins in our series increased and could be considered at least as optimal as those prescribed in the Courage Trial, a study that proved a similar benefit of this optimal medical therapy compared to angioplasty in stable patients with angina." (PMID 28549452, 2017). "ACE inhibitors significantly improve CFR, exercise tolerance, and angina symptoms." (PMID 40041175, 2025). "Beta-blockers and ACE inhibitors were selectively prescribed based on verified indications (LV dysfunction (EF 40%) and recurrent angina) rather than empirically applied." (PMID 40636625, 2025). "Drug treatments were not significantly different between the patients with angina and those with MI, with the exception of ACE inhibitors and calcium antagonists." (PMID 26258408, 2015). "In patients with angina and no obstructive CAD, two randomized placebo-controlled studies of ACE inhibition on coronary microvascular function using intracoronary Doppler flow measurements have been conducted." (PMID 29883497, 2018).
angina (continued). "In this randomized double-blinded placebo-controlled trial of normotensive women with angina and CMD, we found no significant improvement of coronary microvascular function assessed by CFVR in participants treated with the ACE inhibitor, ramipril, compared with placebo." (PMID 29883497, 2018).
Hypercholesterolemia (46 papers, 2008 to 2026). An increased concentration of cholesterol in the blood. "For the secondary outcomes, a significant increase was found in the number of patients diagnosed with of hypercholesterolemia and in prescriptions of ACE inhibitors." (PMID 23734793, 2013). "As for association with lipid disorders, a Saudi study revealed that ACE gene I/D polymorphism has no role in predicting the occurrence and diagnosis of familial hypercholesterolemia." (PMID 27777603, 2016). "Rabbits with induced hypercholesterolemia showed a 15% increase in the serum activity of ACE." (PMID 25050143, 2014). "The relationship between angiotensin converting enzyme (ACE) Insertion/Deletion (I/D) polymorphism and Familial Hypercholesterolemia (FH) has been not fully investigated in all the ethnicities." (PMID 24289455, 2013). "Additionally, enzymatically produced silkworm pupa hydrolysate is reported to possess several bioactive properties, such as inhibiting angiotensin-I converting enzyme (ACE) activity, antioxidant activity, immunomodulatory activity, improving hypercholesterolemia, and anti-tumor activity." (PMID 36230006, 2022).
renal dysfunction (46 papers, 2008 to 2026). "Dexrazoxane may alter anthracycline pharmacokinetics and potentially reduce anticancer efficacy if used early, while ACE inhibitors/ARNIs may increase the risk of hypotension or renal dysfunction when used with VEGF inhibitors." (PMID 41153628, 2025). "From the results of the Change the Management of Patients with HF (CHAMP-HF) registry, older age and renal dysfunction have been reported to be associated with lower prescription rates of HF medications (ACE inhibitors/ARBs/angiotensin-receptor-neprilysin inhibitors, beta-blockers, and MRAs)." (PMID 38683441, 2024). "Additionally, ACE I/D polymorphism has been linked to severe proteinuria and renal dysfunction in preeclamptic patients." (PMID 39194706, 2024). "With regard to ACE SNPs, although the ACE study suggested an association between ACE and renal dysfunction in adult liver recipients who receive TAC, we couldn’t find any significant association between its genotypes and the disposition of TAC too." (PMID 25310192, 2014). "The addition ofolmesartan to patients treated by the combination of ACE inhibitors and betablockers was, however, associated with a significant increase in the occurrenceof the primary endpoint (HR = 1.47; 95% CI, 1.11-1.95; p = 0.006) all-causedeath and renal dysfunction." (PMID 26726045, 2016). "Consistently, several studies demonstrated that administration of angiotensin-converting enzyme (ACE) inhibitor, captopril or enalapril, attenuated renal vasoconstriction during UO and improved postobstructive renal dysfunction in rat and guinea pig." (PMID 37440209, 2023). "Indeed, we found that ACE inhibitors were less frequently prescribed during admission in patients with renal dysfunction." (PMID 30086179, 2018). "Therefore, inhibition of ACE is considered a useful therapeutic approach in the management/treatment of renal dysfunction." (PMID 23847460, 2013). "In these period, ACE inhibitors were administered to all patients in the absence of the contraindications (hyperkaliemia, hypotension), independently of the presence or absence of renal dysfunction." (PMID 25230678, 2014). "Regarding evidence-based drug treatment, patients with severe renal dysfunction were less likely to receive ACE inhibitors, statins, and aspirin than patients with no/mild dysfunction; those with intermediate renal dysfunction were less likely to receive beta-blockers and LMWH." (PMID 25230678, 2014).
viral infection (46 papers, 2015 to 2025). "Other epidemiological investigations discussed the differential incidence of ACE insertion (I)/deletion (D) polymorphisms among populations and its correlations with viral infection, mortality rate, and recovered clinical cases." (PMID 33791232, 2021). "With the capability of inducing elevated expression of ACE2, the cellular receptor for SARS‐CoV‐2, ACE inhibitor treatment may have a controversial role in both facilitating virus infection and reducing pathogenic inflammation." (PMID 35935270, 2022). "The interaction between ACE-2 and SARS-CoV-2 is a vital issue in viral infections, causing the release of inflammatory proteins like TNF-α." (PMID 39854441, 2025). "Since ACE2 acts as an entry pathway for viral infection, blocking this receptor through ACE inhibitors and receptor blockers is promising to prevent viral infection into the lungs and whole body." (PMID 34812049, 2021). "Lymphocytopenia is a characteristic feature in viral disease, which has been attributed to cytopathic effect due to affinity of virus for ACE inhibitors of lymphocytes." (PMID 35283588, 2021). "Viral infections might trigger urticaria by mast cell degranulation via complement activation or vasculitis, which is precipitated by the COVID-19 virus binding to Angiotensin-Converting Enzyme (ACE) 2 receptors on the blood vessels." (PMID 36435635, 2023). "Furthermore, we treated VeroE6 cells with these compounds in the short term, before or after virus infection, to demonstrate that the blockage of ACE/S protein interaction mediated the anti-SARS-CoV-2 infection activity of HT." (PMID 34444960, 2021). "Studies on viral infections such as DENV and H5N1 have explored the inhibition of ACE and kinases involved in the PI3K-AKT-mTOR pathway." (PMID 39858427, 2024). "In the context of viral infections, it has been reported that during Severe acute respiratory coronavirus 2 (SARS-CoV2) infection, miRNA-200c-3p disrupts the regulation of the angiotensin-converting enzyme (ACE), indirectly inhibiting viral infection." (PMID 38249527, 2023). "Accordingly, experiments with SARS-CoV-2 were performed in human ACE-transfected A549 cells (A549ACE2+) to obtain overexpression of ACE2 mRNA/proteins and subsequent efficient virus infection." (PMID 36012747, 2022). "The presence of angiotensin-converting enzyme (ACE) 2 (ACE2), the main receptor for SARS-CoV-2, in human placentas indicates that this organ can be vulnerable for viral infection during pregnancy." (PMID 34338772, 2021). "In contrast, triterpenoid-type compounds (e.g., GPM24, GPM30, GPM32) interacted with a separate subset of targets including ACE, AGTR2, VDR, and were more involved in cardiovascular and renin–angiotensin system-related pathways, as well as metabolic and viral disease modules." (PMID 41471341, 2025). "Notably, although ACE2 receptor mediates virus infection, both SARS-CoV and H7N9 virus downregulate its expression in the lungs shortly after viral infection; however, the expression of ACE remains unaffected." (PMID 34745001, 2021).
Arrhythmia (44 papers, 2005 to 2026). Any cardiac rhythm other than the normal sinus rhythm. "Matrix metalloproteinases (MMPs) and angiotensin-converting enzyme (ACE) have been implicated in the pathogenesis of arrhythmia." (PMID 32555355, 2020). "The CAPRICORN study further described powerful anti‐arrhythmic effects of carvedilol, as it was able to suppress postinfarction arrhythmias even in patients already treated with an angiotensin converting enzyme (ACE) inhibitor." (PMID 32170823, 2020). "In the present study pre-treatment with an oweveHowACE inhibitor (i.e. use of ACE inhibitors before onset of the arrhythmia) improved acute outcome of ECV." (PMID 15667649, 2005). "However, admission for arrhythmia (OR 0.5, p=0.045), ACE inhibitor/angiotensin II receptor blockers use (OR 0.35, p=0.006), digoxin use (OR 0.4, p=0.013) and high albumin (OR 0.9, p=0.019) predicted lower 1-year all-cause mortality." (PMID 35641098, 2022). "The use of oral anticoagulants (OR: 11.80; 95% CI: 1.76, 79.4), ACE inhibitors or AT receptor blockers (OR: 3.87; 95% CI: 1.21, 12.35), and diuretics (OR: 5.29; 95% CI: 1.55, 18.04) had a statistically significant impact on the detection of pacemaker-requiring arrhythmias by an ILR." (PMID 41751365, 2026). "Mechanism studies suggested that ACE inhibitors could prevent AF by affecting the inflammation reaction, reducing the accumulation of the epicardial adipose tissue, and decrease the incidence of arrhythmia via reverse remodeling." (PMID 34859062, 2021). "Both Angiotensin 1 Receptor (AT1R) antagonists as well as Angiotensin Converting Enzyme (ACE) inhibitors have improved cardiac remodeling of the ECM and hypertrophy, together with reduction of arrhythmias, in pre-clinical testing." (PMID 35600469, 2022). "Twelve patients (35%) were affected by diastolic dysfunction, ventricular and/or atrial dilatation, history of arrhythmia, and CHF and all were on stable ACE inhibitor or diuretic or beta-blocker treatment." (PMID 30356378, 2018). "Maintenance therapy combined diuretic, angiotensin-converting enzyme (ACE) inhibitor and anti-vitamin K. In the month of November 2014 the patient had iterative episodes requiring the delivery of electric shocks by the AID, without the sensation of palpitations suggestive of episodes of arrhythmias." (PMID 28761607, 2017).
ischemic stroke (44 papers, 2005 to 2025). A stroke disorder caused by obstruction of blood flow to the brain, due to thrombotic (local blood clot formation) or embolic (due to a blood clot or other material traveling from another site) event. "MR analyses using genetic proxies for ACE inhibition and calcium channel blockade showed protective associations with overall ischemic stroke risk." (PMID 39628323, 2024). "Genetically proxied ACE inhibition and calcium channel blockade were both associated with better functional outcomes after ischemic stroke." (PMID 39628323, 2024). "In ischemic stroke patients, the ACE D allele was associated with high total cholesterol and low-density lipoprotein levels, indicating a possible biomarker for early prevention." (PMID 37238156, 2023). "It has been seen that the co-occurrence of at least one AT1R 1166C allele with the homozygous ACE D/D was more frequent in ischemic stroke patients compared to normal ones." (PMID 34834033, 2021). "The classical axis of the RAS has been widely implicated in ischaemic stroke pathology through becoming over-activation of the Angiotensin Converting Enzyme/Angiotensin II/Angiotensin II receptor type I (ACE/Ang II/AT1R) arm." (PMID 30816157, 2019). "The homozygous ACE D/D polymorphism was investigated in a total of 2 studies covering India in 693 subjects (355 ischemic stroke cases; 338 controls) providing a pooled OR of 5.00 (95% CI, 1.17–21.37, p = 0.03) with a recessive random-effects model." (PMID 23505425, 2013). "A large number of studies have reported the association between the I/D polymorphism of ACE gene and the risk of ischemic stroke, but the results were inconclusive." (PMID 23049705, 2012). "The results of our meta-analysis indicate that the D allele of ACE I/D polymorphism is a low-penetrance susceptibility marker of ischemic stroke." (PMID 23049705, 2012). "The D allele of this polymorphism has been associated with elevated serum ACE level in a codominant pattern and has been investigated as a potential susceptibility factor for ischemic stroke." (PMID 23049705, 2012). "Overall, the variant genotypes of ACE I/D polymorphism were associated with a significantly higher risk of ischemic stroke in different genetic models when all the eligible studies were pooled into the meta-analysis." (PMID 23049705, 2012). "Moreover, a meta-analysis indicated that the ACE D allele is associated with an increased risk of ischemic stroke in Asians but with a borderline association for Caucasians." (PMID 39591456, 2024). "Abnormal PAI-1 and ACE expression levels, which are the target genes associated with the miRNAs examined in this study, may affect the thrombosis pathway and increase ischemic stroke risk." (PMID 33255549, 2020). "Our study finds a high risk of ACE/DD variant in South Asians (OR 5.00: 95% CI, 1.17–21.37) which accounts for a five-fold increase in the risk of overall ischemic stroke per copy of the risk allele of the ACE DD variant relative to Europeans (OR 1.15: 95% CI, 1.06–1.25)." (PMID 23505425, 2013). "Given the important roles of ACE in the pathogenesis of cerebrovascular disease, it is biologically plausible that ACE polymorphism may modulate the risk of ischemic stroke." (PMID 23049705, 2012). "The ACE-DD genotype (OR = 3.71, 95% CI = 1.02–13.5; P < 0.05) and D allele (OR = 2.07, 95% CI = 1.06–4.03; P < 0.05) were significantly more common in patients than in controls, indicating that it is a risk factor for the development of ischemic stroke in hypertensive individuals." (PMID 37034069, 2023). "Regarding the ACE polymorphism, the D variant has been associated with an increase of pro-atherosclerotic properties of conventional cardiovascular risk factors as well as worse functional outcome of ischemic stroke, especially in Asians compared to Caucasians." (PMID 35330428, 2022).